RN7SKP80 (RN7SK pseudogene 80)
Gene: Miscellaneous RNA gene on chromosome 22 (42,565,048 to 42,565,330, reverse strand). Ensembl gene ENSG00000202058.
Homologues: Orthologues: chimpanzee 7SK (95% identical). Paralogues in human: 7SK (93% identical), RN7SKP203 (85% identical), RN7SKP187 (84% identical), RN7SKP118 (84% identical), RN7SKP176 (84% identical), RN7SKP48 (84% identical), RN7SKP9 (84% identical), RN7SKP185 (83% identical), RN7SKP174 (83% identical), RN7SKP246 (83% identical), RN7SKP255 (83% identical), RN7SKP160 (82% identical), and 283 more.
Diseases named in the same sentence as RN7SKP80 in open-access papers:
RN7SKP80 is named in the same sentence as 4 diseases in open-access papers, as found by Europe PMC text mining. Sharing a sentence is not in itself a finding about the gene and the disease. The quoted sentences say what the papers report.
lung adenocarcinoma (1 paper, 2025). A carcinoma that arises from the lung and is characterized by the presence of malignant glandular epithelial cells. "The RN7SKP255 gene was found to be upregulated in lung adenocarcinoma compared with adjacent non‐tumorous tissue while RN7SKP80 plays a contributing factor in distinguishing pancreatic cancer from normal tissue." (PMID 40788820, 2025).
RN7SKP80 also shares sentences with these, for which no sentence is quoted: cancer (1 paper); leukemia (1); pancreatic cancer (1).